ZFYVE19 (zinc finger FYVE-type containing 19)
Description:
Key regulator of abscission step in cytokinesis: part of the cytokinesis checkpoint, a process required to delay abscission to prevent both premature resolution of intercellular chromosome bridges and accumulation of DNA damage. Together with CHMP4C, required to retain abscission-competent VPS4 (VPS4A and/or VPS4B) at the midbody ring until abscission checkpoint signaling is terminated at late cytokinesis. Deactivation of AURKB results in dephosphorylation of CHMP4C followed by its dissociation from ZFYVE19/ANCHR and VPS4 and subsequent abscission.
Synonyms: ANCHR; MPFYVE; FLJ14840; PFIC9
Tractability: PROTAC: UniProt records ubiquitination sites on it; ubiquitination databases record sites on it; its protein half-life has been measured.
Gene: Protein-coding gene on chromosome 15 (40,807,086 to 40,815,084, forward strand). Ensembl gene ENSG00000166140.
Subcellular location: Cytoplasm, cytoskeleton, microtubule organizing center, centrosome; Cleavage furrow; Midbody, Midbody ring
Gene Ontology:
Molecular function: phosphatidylinositol-3-phosphate binding; protein binding; metal ion binding
Biological process: midbody abscission; mitotic cytokinesis checkpoint signaling; negative regulation of cytokinesis
Cellular component: centrosome; cleavage furrow; midbody; Flemming body
Genetic constraint (gnomAD): Loss-of-function variants: 50 observed, 61.47 expected, observed/expected ratio (o/e) 0.81, 90% interval 0.65 to 1.03. The upper end of that interval is the gene's LOEUF score, 1.03, which puts it in group 4 of 6, group 1 being the genes least tolerant of losing a copy. Missense variants: 630 observed, 589.87 expected, observed/expected ratio (o/e) 1.07, 90% interval 1 to 1.14. Synonymous variants: 242 observed, 231.26 expected, observed/expected ratio (o/e) 1.05, 90% interval 0.94 to 1.16.
Homologues: Orthologues: chimpanzee ZFYVE19 (99% identical), macaque ZFYVE19 (94% identical), rabbit ZFYVE19 (72% identical), dog ZFYVE19 (70% identical), guinea pig ZFYVE19 (70% identical), pig ZFYVE19 (69% identical), mouse Zfyve19 (67% identical), rat Zfyve19 (63% identical), tropical clawed frog zfyve19 (46% identical), zebrafish zfyve19 (44% identical), Drosophila melanogaster CG6051 (11% identical), Caenorhabditis elegans lst-2 (7% identical). Paralogues in human: ZFYVE26 (19% identical), RUFY3 (16% identical), PLEKHM2 (15% identical), RUFY1 (15% identical), RUFY2 (14% identical), ZFYVE28 (13% identical), RUNDC3A (11% identical), ZFYVE1 (10% identical), SNX29 (10% identical), RUNDC3B (10% identical), ZFYVE16 (9% identical), PLEKHF1 (7% identical), and 1 more.
Diseases named in the same sentence as ZFYVE19 in open-access papers:
ZFYVE19 is named in the same sentence as 7 diseases in open-access papers, as found by Europe PMC text mining. Sharing a sentence is not in itself a finding about the gene and the disease. The quoted sentences say what the papers report.
cholestasis (3 papers, 2021 to 2025). Impairment of the bile flow caused by obstruction within the liver, or outside the liver in the bile duct system. "Biallelic mutations in ZFYVE19 can lead to high serum GGT cholestasis and ductal plate malformations (DPM) or congenital liver fibrosis." (PMID 37324459, 2023). "Herein we report another patient with cholestasis due to a novel nonsense homozygous pathogenic variant of the ZFYVE19 gene inherited from the heterozygous parents, and further investigate the possible underlying cholestatic pathomechanism." (PMID 33853651, 2021).
ciliopathy (1 paper, 2025). A genetic disorder of the cellular cilia or the cilia anchoring structures, the basal bodies, or of ciliary function. "PFIC9 is caused by a variant in the ZFYVE19 gene that encodes for the Zinc Finger FYVE-Type Containing 19 protein; the variant results in a ciliopathy with elevated γGT." (PMID 39984942, 2025).
esophageal cancer (1 paper, 2025). A primary or metastatic malignant neoplasm involving the esophagus. "In contrast, IGFL1P1, LRRC57A-AS1, SNHG3, ULK3 and ZFYVE19 showed poor expression in esophageal cancer tissues but high expression in the combined treatment group." (PMID 41326355, 2025). "Decreased levels of COL4A1, DEK, GINS1, HPCAL1, KIF4A and RBMX predicted longer survival in esophageal cancer patients, while overexpression of IGFL1P1, LRRC57A-AS1, SNHG3, ULK3 and ZFYVE19 correlated with longer survival." (PMID 41326355, 2025).
liver cirrhosis (1 paper, 2025). "Subsequent whole exome sequencing revealed the diagnosis of liver cirrhosis caused by familial cholestasis related to a mutation in the ZFYVE19 gene." (PMID 39991705, 2025).
liver disease (1 paper, 2021). "Due to the possible role of ZFYVE19 in cilia function and the unprecedented coexistence of a coincidental hereditary sterol disorder in our case, continuous monitoring will be necessary to substantiate type of liver disease progression and/or possible emergence of a multisystemic involvement." (PMID 33853651, 2021).
sitosterolemia (1 paper, 2021). A rare autosomal recessive sterol storage disease characterized by the accumulation of phytosterols in the blood and tissues. "This was in agreement with the diagnosis of sitosterolemia (OMIM #210250) coincidental with the associated cholestatic pattern due to ZFYVE19 defect." (PMID 33853651, 2021).
ZFYVE19 also shares sentences with these, for which no sentence is quoted: Salmonella Infections (1 paper).